PPARG (peroxisome proliferator activated receptor gamma)
Diseases named in the same sentence as PPARG in open-access papers (continued):
Sharing a sentence is not in itself a finding about the gene and the disease.
diabetic nephropathy (67 papers, 2005 to 2026). "Pro12Ala polymorphism in the PPARG gene has also been linked to decreased risk and severity of diabetic nephropathy, emphasizing the role of genetics in the development of the illness." (PMID 40435181, 2025). "All three members of the PPAR subfamily, PPARα, PPARβ/δ, and PPARγ, have been implicated in many renal pathophysiological conditions, including acute kidney injury, diabetic nephropathy, and chronic kidney disease, among others." (PMID 35308207, 2022). "On the other hand, the study has shown that PPARγ single nucleotide polymorphism (SNP) is associated with the risk of diabetic kidney disease." (PMID 29849705, 2018). "Among others the peroxisome proliferator-activated receptor (PPARγ) gene has been associated with the risk of diabetic nephropathy." (PMID 25889595, 2015). "The aim of our study was to find out the role of ACE ID and PPARG P12A polymorphisms in genetic susceptibility of diabetic nephropathy in south Indian population." (PMID 24282791, 2013). "Furthermore, genetic studies have linked the PPARγ Pro12Ala polymorphism to susceptibility to diabetic nephropathy." (PMID 41438090, 2025). "Some studies have found that PPARG is a risk of progression of diabetic nephropathy in China." (PMID 33178322, 2020). "In diabetic kidney disease, the reduced cell proliferation and fibronectin expression or decreased oxidative stress and renal fibrosis were associated with expression changes of PPARγ and p38MAPK." (PMID 29849705, 2018). "The vascular genes ACE (Angiotensin-converting enzyme), and PPARG (peroxisome proliferator activated receptor gamma) are involved in alterations in vascular endothelium, and are suggested to play a role in the susceptibility of diabetic nephropathy." (PMID 24282791, 2013). "Hence, additional studies considering gene-gene and gene-environment interactions should be investigated to estimate the overall risk of the ACE and PPARG genes in the pathogenesis of diabetic nephropathy." (PMID 24282791, 2013). "Hence we hypothesise that the EGFR plays a role in the development of diabetic nephropathy as well as in the associated sodium and water retention, which is exacerbated by concomitant treatment with PPARγ agonists." (PMID 23533381, 2013). "Elevated PON1 levels mitigated oxidative stress and inhibited cell death,thereby promoting cell growth and alleviating diabetic nephropathy throughactivation of the PPARγ signaling pathway." (PMID 40834279, 2025). "PPARγ agonists have a beneficial impact on several kidney illnesses, such as diabetic nephropathy (DN), polycystic kidney disorders, IgA nephropathy, chemotherapy-associated kidney damage, ischemic renal injury, and age-related kidney diseases." (PMID 40435181, 2025). "It has been demonstrated that PPARG agonists, such as thiazolidinediones, enhance renal outcomes in diabetic nephropathy by increasing insulin sensitivity, lowering inflammation, and lowering albuminuria." (PMID 40435181, 2025). "PPARγ also confers renoprotective effects by suppressing the development and progression of diabetic nephropathy." (PMID 41438090, 2025). "A substantial body of evidence confirms that the PPAR signaling pathway is critically involved in the pathogenesis and progression of kidney diseases, and PPARγ agonists exhibit beneficial therapeutic effects in diabetic nephropathy and other renal disorders." (PMID 40442892, 2025). "The disease-associated genes like PI3K-AKT, PPARG and PTGS2 have biological importance in diabetic nephropathy." (PMID 40435181, 2025). "PPARγ agonists, indeed, exert protective effects against various kidney diseases including diabetic nephropathy." (PMID 37338602, 2023). "For example, astragaloside IV was reported to attenuate podocyte apoptosis by inhibiting oxidative stress via activating the PPARγ-Klotho-FoxO1 signaling pathway, thereby ameliorating diabetic nephropathy." (PMID 36339588, 2022).
diabetic nephropathy (continued). "Overexpression of TUG1 alleviates extracellular matrix accumulation, including TGF-β1, collagen IV, and fibronectin in diabetic nephropathy through a mechanism dependent on PPARγ." (PMID 32368256, 2020). "A recent study demonstrated that TUG1 inhibited extracellular matrix (ECM) accumulation through post-transcriptional modification of PPARγ, which suggests a new insight for diabetic nephropathy." (PMID 32368256, 2020). "The significance of PPARγ was also observed in Pparg null mice wherein these mice eventually developed diabetic nephropathy." (PMID 33511131, 2020). "Previous studies have reported that miR-27a promotes renal tubulointerstitial fibrosis, podocyte injury and mesangial cell injury by suppressing PPARγ in diabetic nephropathy." (PMID 29416678, 2018). "In conclusion, our study demonstrates a novel mechanism that reducing CDK5 activity inhibits tubulointerstitial fibrosis by blocking ERK1/2/PPARγ-mediated EMT in diabetic nephropathy." (PMID 27145370, 2016). "The present results demonstrated that CDK5 promoted renal tubulointerstitial fibrosis through enhancing phosphorylated ERK1/2 and PPARγ in diabetic nephropathy." (PMID 27145370, 2016). "Although the role of PPARγ in treating diabetic kidney disease was extensively investigated since PPARγ was discovered, the chief mechanism is roughly focused on the inhibition of inflammation and oxidative stress with poorly understood molecular mechanisms." (PMID 24624137, 2014). "Actually, PPARγ activation not only ameliorates diabetic kidney disease, but it also protects kidneys from a variety of other acute and chronic insults." (PMID 24624137, 2014). "The present review was undertaken to address the advancements and the therapeutic potential of these newly developed PPARγ agonists in dealing with diabetic kidney disease." (PMID 24624137, 2014). "Although several NHRs, including peroxisome proliferator-activated receptor-γ (PPARγ) and PPARα, demonstrate a renoprotective effect in the context of diabetic nephropathy (DN), the expression and role of other NHRs in the kidney are still unrecognized." (PMID 24465611, 2014). "The 12Ala isoform of PPARγ had been found to have a protective role against diabetic nephropathy, another common T2DM complication." (PMID 23559865, 2013). "Second, although activation of PPARγ is well known to have organ‐protective actions such as reduction of cardiovascular events and proteinuria and delaying the progression of diabetic nephropathy, the mediator of PPARγ is still unclear." (PMID 23608606, 2013). "Corni Fructus has the potential to protect the animals from diabetic nephropathy by amelioration of oxidative stress and stimulation of PPARγ expression." (PMID 24062795, 2013). "The involvement of this molecule on renal impairment is confirmed by the fact that PPARγ agonists can slow or even prevent the progression of various kidney injuries including diabetic nephropathy via multiple mechanisms involving activation of PPARγ in the kidney and other tissue." (PMID 37338602, 2023). "CASC2/miR-9-5p/PPARγ alleviates the high glucose-induced cell injury in diabetes nephropathy." (PMID 35935642, 2022). "For instance, PPARγ was downregulated in diabetic nephropathy." (PMID 36339588, 2022). "Moreover, TUG1 reduces the accumulation of extracellular matrix accumulation by antagonizing the effect of miRNA-377 in downregulating PPARγ expression in diabetic nephropathy." (PMID 34097717, 2021). "The lncRNA expression profile provides a basis for understanding the renal-specific protective mechanism of PPARγ agonists and may provide a theoretical basis for new therapeutic strategies for diabetic nephropathy." (PMID 32025515, 2020). "And the aim of this study is to elucidate the novel renoprotective molecular mechanism of PPARγ agonists and to propose lncRNA targets for diabetic nephropathy treatment, which may provide a new approach to avoid systemic side effects." (PMID 32025515, 2020).
diabetic nephropathy (continued). "In vivo, PPARγ agonist induced reductions of chemerin and/or CMKLR1 in diabetic rats which might be associated with the ameliorations of diabetic nephropathy." (PMID 30873215, 2019). "In livers of diabetic nephropathy rat and db/db mice, the protein level of PPARγ was shown to decrease, and restoring PPARγ gene expression to baseline could improve metabolic disorders." (PMID 30463189, 2018). "Danhong injection could delay the progress of diabetic kidney disease, and the effect might be achieved in part by activating the PPARγ signaling pathway." (PMID 29849705, 2018). "Thus, in line with the role of PPARγ in metabolic homeostasis, Pparg null-mice first represent a potent model for studying the initiation and the development of diabetic nephropathy." (PMID 28182703, 2017). "Although, the mechanisms by which the PPARG P12A polymorphism contributes to diabetic nephropathy is not yet elucidated completely." (PMID 24282791, 2013). "In conclusion, the ACE and PPARG genes do not have a key role in conferring risk for diabetic nephropathy." (PMID 24282791, 2013). "Furthermore, they have a synergistic effect on limiting high-glucose-induced upregulation of inflammatory and fibrotic pathways when used with PPARγ agonists, which is likely to ameliorate the tubulointerstitial pathology observed in diabetic nephropathy." (PMID 23533381, 2013). "In conclusion, the ACE and PPARG genes do not play a key role in conferring risk for diabetic nephropathy." (PMID 24282791, 2013). "In the diabetic nephropathy mice experiment model, troglitazone a peroxisome proliferator -activated receptor gamma (PPAR gamma) agonists, ameliorate renal fibrotic lesions through reverse high glucose induced expressions of GSK-3β and inhibition epithelial-mesenchymal transition." (PMID 22243669, 2012). "BSA is commonly used as a control for evaluating the effect of AGEs in experimental researches such as in vitro study for diabetic nephropathy with cultured mesangial cells, and proximal tubular cell injury via peroxisome proliferator-activated receptor-gamma activation." (PMID 22511847, 2012). "Indeed, all three PPAR subtypes share common lipid-lowering properties, and PPARα and PPARγ exert similar renoprotective effects in animals or humans with diabetic nephropathy." (PMID 20671947, 2010). "Recent studies have suggested that peroxisome proliferator-activated receptor-γ (PPARγ) synthetic agonist thiazolidinediones, such as rosiglitazone, may prevent or attenuate diabetic nephropathy in animal models." (PMID 19609456, 2009). "Therefore, we speculated that Danhong injection delays the development of diabetic kidney disease partially through the p38MAPK/PPARγ signaling pathway." (PMID 29849705, 2018). "Hence targeting the EGFR in combination with the PPARγ agonist has the potential to be beneficial in regulating nephromegaly, matrix expansion, and fibrosis in addition to excessive sodium reabsorption observed in diabetic nephropathy." (PMID 23533381, 2013). "Previous research has shown that activators of PPARγ and PGC‐1α can protect against diabetic nephropathy and suppress inflammation by inhibiting the NF‐κB signalling pathway, both in diabetic mice and in a human proximal tubular cell line [S2]." (PMID 41588476, 2026). "In diabetic nephropathy, CASC2 reduces HG-induced podocyte injury by mediating the miR-9-5p/PPARγ axis." (PMID 38405620, 2024). "Numerous publications have discussed the correlation between PPARG Pro12Ala and CKD; the results show that compared with the C/C genotype, the G/G or G/C genotype of PPARG Pro12Ala is a protective factor against diabetic nephropathy or CKD." (PMID 32604723, 2020).
diabetic nephropathy (continued). "We have reported that PPARγ agonist ciglitazone improved GFR and glomerular architecture in diabetic nephropathy, in part, by normalizing tissue levels of homocysteine in the glomerulus." (PMID 20613990, 2010). "In mesangial cells, the PPARγ agonist thiazolidinediones inhibit TGF-β1-induced fibronectin expression and ameliorate diabetic nephropathy." (PMID 19609456, 2009). "PPARγ seems to produce improvement in the epithelial-to-mesenchymal transition and tubulointerstitial fibrosis by up-regulating FAK activation to ameliorate diabetic nephropathy." (PMID 32390845, 2020). "Studies have shown that PPARγ agonists could ameliorate renal fibrotic lesions in diabetic nephropathy and nondiabetic chronic kidney diseases." (PMID 23544048, 2013).
gastric cancer (67 papers, 2000 to 2025). A primary or metastatic malignant neoplasm involving the stomach. "An in vivo animal study determined that heterozygous (PPARγ+/−) knockout mice were more susceptible to N-methyl-N-nitrosourea-induced gastric carcinoma than homozygotes (PPARγ+/+), but troglitazone only reduced the incidence of gastric cancer in homozygotes." (PMID 22936949, 2012). "In the future, additional studies are warranted to elucidate the link between bioactive food components and cancer risk at sites with moderate to high PPARG expression such as the digestive tract (specifically gastric cancer) with high levels of bioactive food components." (PMID 33477496, 2021). "Previous research has illustrated that the PPARγ allele may be involved in the development, differentiation, and metastasis of gastric cancer in Turkey." (PMID 31341536, 2019). "PPARG activation has been shown to induce apoptosis in various cancer types, including esophageal cancer, non-small cell lung carcinoma, and gastric cancer." (PMID 40564064, 2025). "The differences in the expression of hub genes, PTGS2, MMP9, MMP2, and CXCR4 genes were higher than normal gastric tissues in gastric cancer, and PPARG gene was lower than normal gastric tissues." (PMID 38457601, 2024). "Associations of ABCC8/KCNJ11, DPP4, GLP1R, GPD2, PPARG, PRKAB1, and SLC5A2 with anal carcinoma, cardia cancer, gastric cancer, HCC, ICC, pancreatic cancer, and rectum cancer were revealed in two-sample MR analyses." (PMID 38504335, 2024). "PPARγ agonists showed dose-dependent inhibitory effects on the proliferation of the gastric cancer cells." (PMID 36106123, 2022). "The purpose of this study was to investigate the association of PPARγ, PPARGC1A, and PPARGC1B variants with the risk of gastric cancer (GC)." (PMID 36587194, 2022). "PPAR Research has retracted the article titled “Rosiglitazone Suppresses the Growth and Invasiveness of SGC-7901 Gastric Cancer Cells and Angiogenesis In Vitro via PPARγ Dependent and Independent Mechanisms” due to figure duplication." (PMID 32952539, 2020). "After being activated by ligands, PPARγ can not only inhibit the proliferation of gastric cancer growth, but also prevent the development and growth of gastric cancer." (PMID 29483923, 2018). "Several in vitro studies have found that PPARγ activation results in cell cycle arrest and/or apoptosis of gastric cancer cells." (PMID 22936949, 2012). "On experimental investigation, it was found that PPARγ suppresses gastric carcinogenesis and that PPARγ ligands such as troglitazone and ciglitazone are potential agents for gastric carcinoma because they inhibit PPARγ-dependant cell proliferation." (PMID 20885923, 2010). "Irrespective of the differentiation status of the tumour, strong expression of immunoreactive PPARγ was observed in surgically resected human gastric cancer tissues." (PMID 15583697, 2005). "We used reverse transcription-polymerase chain reaction and Northern and Western blot analyses to demonstrate PPARγ expression in four human gastric cancer cell lines." (PMID 11044367, 2000). "PPARγ agonists (troglitazone and 15-deoxy-Δ12,14-prostaglandin J2) showed dose-dependent inhibitory effects on the proliferation of the gastric cancer cells, and their effect was augmented by the simultaneous addition of 9-cis retinoic acid, a ligand of RXRα." (PMID 11044367, 2000). "We report the PPARγ expression in human gastric cancer, and the effect of PPARγ ligands on proliferation of gastric carcinoma cell lines." (PMID 11044367, 2000). "Besides, it was shown that trastuzumab-resistant gastric cancer cells displayed PPARγ- and PER1-controlled circadian fluctuations in their glycolytic activity." (PMID 35890319, 2022). "We transfected with gastric cancer cell lines with miR-193a-3p and transfected supernatant was collected to co-culture with 3T3-L1, the adipogenesis specific genes C/EBPα, PPARγ and Perilipin-1 were evidently elevated, and DLK1 was down-regulated in mimic group." (PMID 35541892, 2022).